BRCA1 (BRCA1 DNA repair associated)
Diseases named in the same sentence as BRCA1 in open-access papers (continued):
Sharing a sentence is not in itself a finding about the gene and the disease.
breast cancer (continued). "Data provided by The Consortium of Investigators of Modifiers of BRCA1/2 (CIMBA) indicated that the FGFR2 locus associated with breast cancer in BRCA2 mutation carriers but not in BRCA1 mutation carriers." (PMID 24171766, 2013). "Treatment with cucurbitacin B can inhibit cellular proliferation of these mutant cells and the BRCA1-defective parental cells, suggesting that cucurbitacin B could be an effective anticancer agent properly used for BRCA1-defective breast cancer." (PMID 23393598, 2013). "This variant, PALB2 c.2993G>A, has previously been identified in studies examining the role of PALB2 in multiple-case breast cancer families that are not known to carry BRCA1 or BRCA2 mutations." (PMID 23448497, 2013). "Additionally, promoter hypermethylation occurs in only a small subset of the majority of sporadic breast cancers that exhibit BRCA1 downregulation." (PMID 24705161, 2013). "To determine whether common genetic variants modify breast cancer risk for BRCA2 mutation carriers, we previously conducted a GWAS of BRCA2 mutation carriers from the Consortium of Investigators of Modifiers of BRCA1/2 (CIMBA)." (PMID 23544012, 2013). "The similar phenomenon was also observed in familial breast cancer patients without a detectable BRCA-1 or BRCA-2 mutation." (PMID 23556484, 2013). "Because the BRCA1-depleted MCF7 cells used in this study mimic the physiological status of BRCA1 in breast cancers, we asked whether some translationally deregulated mRNAs encode potential therapeutic targets." (PMID 23805307, 2013). "A cohort of 84 HBOC individuals (negative for BRCA1/2-founder mutations and pre-screened for the most common breast cancer genes) and 36 healthy controls were analysed with a genome-wide SNP array." (PMID 23967248, 2013). "Previous studies conducted in Taiwanese population showed that the mutation of BRCA1 gene does not play a significant role in the occurrence of breast cancer." (PMID 23405268, 2013). "Wang et al85 studied 360 samples from Han Chinese and reported that, by interacting with BRCA1 rs4793191 and BRCA2 rs9567623, the ATM polymorphism rs611646 might have a role in breast cancer risk." (PMID 23318652, 2013). "Subsequent studies have reported that BRCA1 hypermethylation is not specific to ER−ve breast cancers and that the gene expression profiles of BRCA1 mutated and methylated cancers differ." (PMID 23341493, 2013). "Furthermore, PTEN and BRCA1 are both downregulated in metastatic breast cancer tissues, and that is negatively correlated with miR-2b expression in these tissues." (PMID 23945289, 2013). "Given the potential benefits versus harms of this testing, the result of our study suggest that PALB2 c.1592delT should be a routine part of the genetic counseling protocol for Finnish high-risk breast cancer cases tested negative for mutations in BRCA1/BRCA2." (PMID 23941127, 2013). "Mean percentage values of cells showing the reaction for BRCA1 were 30.0 % in breast cancer group vs. 37.5 % in BRCA1 mutation carriers without breast cancer." (PMID 23553196, 2013). "Prophylactic oophorectomy can prevent the development of breast cancers in BRCA1 mutation carriers in whom the main types of breast cancer are ER negative." (PMID 24160328, 2013). "Over the last year, five studies have investigated the role of SLX4 in familial BRCA1/2 mutation-negative breast cancer cases." (PMID 23840564, 2013). "Here we present our SLX4 sequencing results in 738 BRCA1/2 mutation-negative breast cancer patients and a functional analysis of select SLX4 variants." (PMID 23840564, 2013). "Four PALB2 p.Q775X positive cases were also identified in a subsequent study involving 564 (0.7%) breast cancer cases not selected for family history of cancer, which also showed that 6% of cases harbored common BRCA1, BRCA2 or CHEK2 mutations." (PMID 23302520, 2013).
breast cancer (continued). "The results indicated that cucurbitacin B inhibits cellular proliferation, migration, invasion and ability of anchorage-independent growth of the BRCA1 knocked-down breast cancer cells while this compound exerts a minimal effect on the wild type BRCA1 breast cancer cells." (PMID 23393598, 2013). "As the same trend is seen in the general population, this could support the hypothesis that the majority of ER+ BRCA1 breast cancers are just incidental." (PMID 23704984, 2013). "Li et al16 reported that age at onset of BRCA1-associated breast cancer was significantly earlier as compared with BRCA2-associated and sporadic breast cancers (median age: 36.1 years in BRCA1-associated, 42.7 years in BRCA2-associated, and 47.3 years in sporadic breast cancer)." (PMID 23318652, 2013). "In a large US study which included 1727 breast cancer female patients younger than age 65 at diagnosis, estimates of BRCA1 prevalence were the highest in Hispanic patients (3.5%), followed by non-Hispanic whites (2.2%), African Americans (1.3%), and Asian Americans (0.5%)." (PMID 24348557, 2013). "Here we should depict the fact, that the mutations in the BRCA1 gene do not constitute a pathogenic factor, but potentially predispose to breast cancer." (PMID 23941236, 2013). "Current findings suggest that the interactions between breast cancer susceptibility SNPs and breast cancer risk are not as strong as those for BRCA1 or BRCA2 gene mutation." (PMID 24289300, 2013). "Interestingly, the MCF7 breast cancer cell line used in our study strongly expresses miR-335 and has reduced BRCA1 foci levels." (PMID 23696749, 2013). "Our findings suggests that BRCA1 promoter methylation is a better predictor of recurrence and survival than factors such as tumor size, lymph node metastasis, histological grade, and age in early-stage breast cancer." (PMID 23405268, 2013). "To determine whether the breast cancer association with rs9348512 was limited to BRCA2 mutation carriers, we compared results to those in the general population genotyped by BCAC and to BRCA1 mutation carriers in CIMBA." (PMID 23544012, 2013). "Both high-grade, serous ovarian and basal-like breast cancer are seen in women with mutant BRCA1." (PMID 23536770, 2013). "Until recently, BRCA1 and BRCA2 were the only genes known to confer a considerable risk of ovarian cancer (in conjunction with breast cancer) with two recent studies reporting that 13.3–14.1% of unselected high grade ovarian cancers are accounted for by mutations in one of these two genes." (PMID 23372765, 2013). "We sequenced the entire coding region of the SLX4 gene in 738 BRCA1/2 mutation-negative familial breast cancer patients and found 26 previously known and 14 novel coding variants." (PMID 23840564, 2013). "The study included breast surgery patients that were BRCA1/2 mutation carriers without breast cancer (n = 23), had BRCA1/2 (n = 28) or sporadic (n = 21) breast cancer, or required non-cancer-related mammoplasty (n = 34)." (PMID 24188377, 2013). "Positive expression of BRCA1 protein was present in nine patients (90.0 %) in the group with breast cancer and in six patients (75.0 %) in BRCA1 mutation carriers without breast cancer." (PMID 23553196, 2013). "We suggest that survivin could be an important target of cucurbitacin B in BRCA1 defective breast cancer cells." (PMID 23393598, 2013). "Mean values of the intensity of immunostaining for BRCA1 protein were 1.0 ou/μm2 in the group with breast cancer versus 1.3 ou/μm2 in BRCA1 mutation carriers only without breast cancer." (PMID 23553196, 2013).
breast cancer (continued). "The other two cell lines are endogenous mutant BRCA1 breast cancer cells." (PMID 23393598, 2013). "However, a study on BRCA1 and BRCA2, two genes well-known to be involved in human breast cancer, showed associations of these genes with mammary tumours in English Springer Spaniels." (PMID 23574728, 2013). "Another study showed also lack of association of the rs2910164 SNP with breast cancer risk in a series of BRCA1 and BRCA2 mutation carriers." (PMID 23586049, 2013). "Prevalence of BRCA1 or BRCA2 germ line mutations varies considerably among ethnic groups, and in some countries, founder mutations are responsible for a significant proportion of breast cancer cases." (PMID 23683081, 2013). "We report here that hypermethylation of the BRCA1 gene promoter is present in 56% (78 of 139) of Taiwanese women with early-stage sporadic breast carcinomas, which is significantly higher than previously reported frequencies for this alteration in unselected sporadic breast tumors." (PMID 23405268, 2013). "Using whole-genome comparative genomic hybridization on microarrays, we screened a cohort of women fulfilling criteria for hereditary breast cancer who did not carry BRCA1/BRCA2 mutations." (PMID 22314128, 2012). "We found that among women diagnosed with breast cancer aged 36 to 50 years but with no family history of breast or ovarian cancer, the prevalence of BRCA1 and BRCA2 mutations was similar in TNBC (8.5%) and non-TNBC patients (6.7%)." (PMID 23116406, 2012). "In an attempt to identify germline mutations in additional high risk breast cancer susceptibility genes, we have optimised and applied the GINI method on lymphoblastoid cell lines derived from the blood of women from multiple-case non- BRCA1/2 breast cancer families." (PMID 22703186, 2012). "Cancers defective in DNA repair, specifically cancers with mutations in the breast cancer associated BRCA1 and BRCA2 genes and triple-negative breast cancer (which shares molecular and pathologic features with BRCA1-related breast cancers) appear to be particularly sensitive to inhibition of PARP-1." (PMID 22619725, 2012). "Enhancement of BRCA1 expression by PPARγ has been reported in MCF-7 breast cancer cells." (PMID 22701472, 2012). "Moreover, molecular gene-expression profiling of BRCA1 tumors showed that the tumors have significant similarities with the basal-like subtype of breast cancer." (PMID 23116406, 2012). "Here we report that ever having breastfed and the total duration of breastfeeding conferred substantial reductions in breast cancer risk among BRCA1, but not BRCA2 mutation carriers." (PMID 22405187, 2012). "BRCA1 is heavily implicated in breast cancer in humans, with BRCA1+/− women having a 50% risk of developing breast cancer, while BRCA+/− mice do not exhibit increased susceptibility to cancer." (PMID 22788692, 2012). "This is consistent with the emerging association between an altered luminal progenitor profile in basal breast cancers associated with BRCA1 mutations, rather than the mesenchymal profile seen in breast CSC." (PMID 23056490, 2012). "Despite that lack of knowledge, however, the demand for prophylactic bilateral mastectomy after first breast cancer is increasing not only for mutation carriers but also for women without a BRCA1 or BRCA2 mutation." (PMID 23216834, 2012). "This was true even in subgroups containing women typically considered average risk (for example, no family history of breast cancer, BRCA1/2 mutation negative)." (PMID 23127309, 2012). "In 77 TNBC cases from the United States that were not selected for age or familial breast cancer occurrence, the mutation frequencies were 15.6% for BRCA1 (n = 12) and 3.9% for BRCA2 (n = 3)." (PMID 22666503, 2012). "Two (25%) BRCA2 mutations and no BRCA1 mutation were reported among eight male breast cancer patients in a small study." (PMID 22382806, 2012).
breast cancer (continued). "The interplay between BRCA1 and RHAMM is linked to breast cancer, both through BRCA1 gene mutations in familial breast cancer and low-penetrance genetic variation at the HMMR locus (encoding RHAMM) associated with sporadic breast cancer." (PMID 24278741, 2012). "If one considers just individuals with sporadic TN breast cancer, that is, those without a first or second degree relative with breast or ovarian cancer, 8 out of 103 (8%) had a BRCA1 mutation, and all were under 50 years of age." (PMID 22333603, 2012). "Moving forward, it is critical to carefully investigate the ways in which Internet-based psychoeducation and support resources can be integrated into the delivery of health care services for hereditary breast cancer, such as BRCA1/2 genetic counseling and testing services." (PMID 22257650, 2012). "GWAS in the general population have recently identified eight additional breast cancer susceptibility loci which have not been previously investigated in BRCA1 and BRCA2 mutation carriers." (PMID 22348646, 2012). "Taken together, the results suggest that early onset and familial breast cancer patients in whom TNBC develops are more likely to have mutations in the BRCA1 genes compared with those in whom non-TNBC develops (24.5% versus 11.8%; P = 0.001)." (PMID 23116406, 2012). "A mutation analysis of SLX4 in German or Byelorussian familial cases of breast cancer without detected mutations in BRCA1 or BRCA2 has been completed, with globally negative results." (PMID 22401137, 2012). "Here we report our analysis of RAD51D in 175 ovarian and breast cancer pedigrees, having at least one case of ovarian cancer in which BRCA1 and BRCA2 mutations were previously ruled out." (PMID 22415235, 2012). "Contralateral breast cancer risk in patients from high risk families that tested negative for BRCA1/2 mutations is similar to the risk in patients with sporadic breast cancer." (PMID 23216834, 2012). "However, BRRSO in BRCA1 and BRCA2 mutations carriers has proven to be effective in reducing the rates of ovarian cancer as well as reducing the rates of breast cancer in the under 50 age group." (PMID 22187038, 2012). "Interestingly, the BRCA1 microdeletion identified here appears to be the same as the one identified in a breast cancer Italian patient." (PMID 22691290, 2012). "BRCA1 breast cancers derive from an ER-negative luminal progenitor." (PMID 22082486, 2012). "About 89% of triple-negative breast cancers (defined by deficiency of estrogen-receptor, progesterone receptor, and HER-2 receptor) have wild-type BRCA1, as such, BRCA1 may serve as a therapeutic target for most cases of this difficult breast cancer subtype." (PMID 25969759, 2012). "Misregulation and reduced expression of BRCA1 also contribute to sporadic forms of breast cancer." (PMID 24278741, 2012). "Unlike breast cancer, there are no well-established guidelines linking BRCA1 mutations and individual's predisposition to developing ovarian cancer." (PMID 22685544, 2012). "Of 625 early onset patients, BRCA1 and BRCA2 mutations were detected in 35 (6.4%) of 550 patients without other risks, in 16 (30.2%) of 53 patients with bilateral breast cancer, in one (100%) patient who also had ovarian cancer, and in one (5.3%) of 19 patients with multiple organ cancers." (PMID 22382806, 2012). "Overall mutation of BRCA1/2 genes in high-risk breast cancer patients without family history of breast or ovarian cancer in this study was 8.6%." (PMID 22382806, 2012). "Thus, elucidation of the precise molecular functions of Brca1-Akt pathway will be particularly important to understand tumorigenesis of hereditary and sporadic breast cancer." (PMID 22481935, 2012). "At the germline level, some studies have shown that the single nucleotide polymorphism (SNP) −135G>C (rs1801320) in the 5′ untranslated region (UTR) of RAD51 modifies breast cancer risk in BRCA2 mutation carriers but not in BRCA1 mutation carriers." (PMID 23300655, 2012).
breast cancer (continued). "Our observation that BRCA1-associated hereditary breast cancers often showed high nuclear Kaiso, is in line with the finding that nuclear Kaiso is in general associated with high grade, basal-like and EGFR positive breast cancers." (PMID 22662240, 2012). "In a retrospective cohort study comprising 2,020 women with unilateral breast cancer from 978 families with a BRCA1 or BRCA2 mutation, we could show that contralateral breast cancer depends on the affected BRCA gene and age at onset of the first breast cancer." (PMID 23216834, 2012). "It is important to acknowledge that apart from environmental factor such as betel quid being the prime focus of this study, genetic risk factors such as BRCA1 and BRCA2, lifestyle risk factors such as diet and reproductive risk factors also contribute to breast cancer." (PMID 22937096, 2012). "Review of the spectrum of breast cancer tumor subtypes, which include basal-like, triple-negative and BRCA1-positive tumors, suggest that they have overlapping clinical, pathologic and molecular features, which are different from endocrine responsive breast cancers." (PMID 23039971, 2012). "The breast cancer susceptibility and Fanconi proteins FANCD1/BRCA2, the partner of BRCA2 (PALB2/FANCN), a helicase associated with BRCA1 (FANCJ/BACH1), and several newly identified components including FAN1, FANCO/RAD51C, and FANCP/SLX4 participate in the pathway to respond to and repair DNA damage." (PMID 22693661, 2012). "These BRCA1 defective breast cancers contained expanded luminal progenitor cells." (PMID 24977105, 2012). "Close to 75% of BRCA1-associated breast cancers is either TNBC, basal-like breast cancer or both." (PMID 22666503, 2012). "Subsequently, methylation in the promoter region of BRCA1 has been found in sporadic breast cancer." (PMID 22735547, 2012). "Further studies to elucidate the role of posttranscriptional mechanisms controlling BRCA1/p220 and BRCA1-IRIS mRNA expression in normal and breast cancer cells are required to elucidate the mechanism(s) underlying the development of familial and TN/BL breast cancers." (PMID 22431556, 2012). "There is a lack of studies about the prevalence of BRCA1/2 mutations in male breast cancer in Korea." (PMID 22382806, 2012). "Younger age at first breast cancer was associated with a significantly higher risk of contralateral breast cancer in patients from BRCA1 positive and BRCA1/2 negative families and a trend was observed in patients from BRCA2 positive families." (PMID 23216834, 2012). "Consistent with a mitogenic role for PR in breast cancer, an in vivo preclinical study recently showed that MIF treatment actually prevented the development of mammary carcinogenesis in mice carrying a mutated BRCA1 gene." (PMID 22429491, 2012). "Fu and Liu found the BRCA1 protein is highly expressed in breast cancer, suggesting that the abnormal expression of the BRCA1 has some correlations with the occurrence and growth of breast cancer." (PMID 23276146, 2012). "Importantly, cytoplasmic retention of Brca1 is strongly correlated with activated Akt1 in biopsies from sporadic breast cancer patients." (PMID 22481935, 2012). "It identifies three high-risk population groups (BRCA1/2, BRCAX) which may be important for screening for male breast cancer." (PMID 23146383, 2012).